SLC39A8 (solute carrier family 39 member 8)
Description:
Electroneutral divalent metal cation:bicarbonate symporter of the plasma membrane mediating the cellular uptake of zinc and manganese, two divalent metal cations important for development, tissue homeostasis and immunity. Transports an electroneutral complex composed of a divalent metal cation and two bicarbonate anions or alternatively a bicarbonate and a selenite anion. Thereby, it also contributes to the cellular uptake of selenium, an essential trace metal and micronutrient. Also imports cadmium a non-essential metal which is cytotoxic and carcinogenic. May also transport iron and cobalt through membranes. Through zinc import, indirectly regulates the metal-dependent transcription factor MTF1 and the expression of some metalloproteases involved in cartilage catabolism and also probably heart development. Also indirectly regulates the expression of proteins involved in cell morphology and cytoskeleton organization. Indirectly controls innate immune function and inflammatory response by regulating zinc cellular uptake which in turn modulates the expression of genes specific of these processes. Protects, for instance, cells from injury and death at the onset of inflammation. By regulating zinc influx into monocytes also directly modulates their adhesion to endothelial cells and arteries (By similarity). Reclaims manganese from the bile at the apical membrane of hepatocytes, thereby regulating the activity of the manganese-dependent enzymes through the systemic levels of the nutrient. Also participates in manganese reabsorption in the proximal tubule of the kidney. By mediating the extracellular uptake of manganese by cells of the blood-brain barrier, may also play a role in the transport of the micronutrient to the brain. With manganese cellular uptake also participates in mitochondrial proper function. Finally, also probably functions intracellularly, translocating zinc from lysosome to cytosol to indirectly enhance the expression of specific genes during TCR-mediated T cell activation.
Synonyms: LZT-Hs6; ZIP-8; BIGM103; ZIP8; PP3105; CDG2N
Tractability: Antibody: UniProt places it where antibodies can reach, with high confidence; its Gene Ontology location is reachable by antibodies, with high confidence; UniProt predicts a signal peptide or a membrane-spanning region. PROTAC: ubiquitination databases record sites on it.
Safety:
Unwanted effects reported when the protein is acted on. In parentheses: how it was acted on, where the effect was seen, and who reports it.
alcoholism (source: ClinPGx)
Gene: Protein-coding gene on chromosome 4 (102,251,080 to 102,431,258, reverse strand). Ensembl gene ENSG00000138821.
Subcellular location: Cell membrane; Lysosome membrane; Apical cell membrane; Basolateral cell membrane
Pathways (Reactome):
Transport of small molecules: Zinc influx into cells by the SLC39 gene family
Gene Ontology:
Molecular function: monoatomic cation:bicarbonate symporter activity; zinc ion transmembrane transporter activity; metal ion transmembrane transporter activity; zinc:bicarbonate symporter activity
Biological process: cadmium ion transmembrane transport; cellular detoxification of cadmium ion; extracellular matrix organization; intracellular zinc ion homeostasis; iron ion import across plasma membrane; manganese ion transmembrane transport; mitochondrial manganese ion transmembrane transport; negative regulation of canonical NF-kappaB signal transduction; negative regulation of inflammatory response; plasma membrane selenite transport; regulation of DNA-templated transcription; regulation of membrane potential; zinc ion import across plasma membrane; zinc ion transmembrane transport; zinc ion transport; arginine metabolic process; bicarbonate transport; cartilage homeostasis; cobalt ion transport; intracellular manganese ion homeostasis; intracellular monoatomic cation homeostasis; leukocyte adhesion to arterial endothelial cell; protein N-linked glycosylation; mercury ion transport; metal ion transport; and 1 more
Cellular component: apical plasma membrane; basolateral plasma membrane; lysosomal membrane; organelle membrane; plasma membrane; membrane
Genetic constraint (gnomAD): Loss-of-function variants: 13 observed, 34.34 expected, observed/expected ratio (o/e) 0.38, 90% interval 0.25 to 0.6. The upper end of that interval is the gene's LOEUF score, 0.6, which puts it in group 2 of 6, group 1 being the genes least tolerant of losing a copy. Missense variants: 445 observed, 518.84 expected, observed/expected ratio (o/e) 0.86, 90% interval 0.79 to 0.93. Synonymous variants: 211 observed, 202.36 expected, observed/expected ratio (o/e) 1.04, 90% interval 0.93 to 1.17.
Gene-disease validity (ClinGen):
ClinGen rates the evidence that SLC39A8 causes each of these diseases.
Leigh syndrome (autosomal recessive): Limited. A progressive neurological disease defined by specific neuropathological features associating brainstem and basal ganglia lesions.
Homologues: Orthologues: chimpanzee SLC39A8 (100% identical), macaque SLC39A8 (99% identical), pig SLC39A8 (92% identical), dog SLC39A8 (91% identical), mouse Slc39a8 (89% identical), rat Slc39a8 (88% identical), rabbit SLC39A8 (83% identical), guinea pig SLC39A8 (68% identical), tropical clawed frog slc39a8 (59% identical), zebrafish slc39a8 (28% identical), Caenorhabditis elegans zipt-15 (27% identical). Paralogues in human: SLC39A14 (48% identical), SLC39A10 (32% identical), SLC39A6 (30% identical), SLC39A4 (29% identical), SLC39A12 (28% identical), SLC39A5 (26% identical).
Diseases named in the same sentence as SLC39A8 in open-access papers:
SLC39A8 is named in the same sentence as 178 diseases in open-access papers, as found by Europe PMC text mining. Sharing a sentence is not in itself a finding about the gene and the disease. The quoted sentences say what the papers report.
schizophrenia (42 papers, 2012 to 2025). A major psychotic disorder characterized by abnormalities in the perception or expression of reality. "Here, we discovered a selective potentiator of SLC39A8, a metal transporter associated with inflammatory bowel disease, schizophrenia, and cardiovascular and metabolic disorders." (PMID 41178719, 2025). "SLC39A8 polymorphism has been linked to neurodevelopment and schizophrenia in children, and hypomethylated SLC39A8 has been shown to be overexpressed in preeclampsia." (PMID 38886689, 2024). "For instance, a variant within SLC39A8, a schizophrenia-associated gene with well-described evolutionary properties, is absent from this study due to its low allele frequency." (PMID 37726359, 2023). "Recently, it has been reported that the schizophrenia risk locus SLC39A8 (also known as ZIP8) is involved in N-glycosylation." (PMID 37156804, 2023). "For instance, the GWS schizophrenia risk variant rs13107325 (C/T) within the SLC39A8 gene has been described to be under positive selection of its derived risk T allele in Europeans36,39." (PMID 37726359, 2023). "To elucidate the role of rs13107325 in schizophrenia, we generated a knock-in mouse model by introducing a point mutation at SLC39A8-p.393T, which corresponds to human rs13107325 (SLC39A8-p.Ala393Thr)." (PMID 36056013, 2022). "In summary, we successfully linked the risk missense variant rs13107325 to a featured characteristic of schizophrenia by using the SLC39A8-p.393T knock-in mouse model." (PMID 36056013, 2022). "Among the schizophrenia GWAS hits, a non-synonymous single nucleotide polymorphism (SNP) rs13107325 (C/T), which encodes SLC39A8 p.Ala391Thr, showed robust association with schizophrenia in schizophrenia GWASs." (PMID 36056013, 2022). "The missense variant rs13107325 (C/T, p.Ala391Thr) in SLC39A8 consistently showed robust association with schizophrenia in recent genome-wide association studies (GWASs), suggesting the potential pathogenicity of this non-synonymous risk variant." (PMID 36056013, 2022). "While further analysis of the schizophrenia locus in the SLC39A8 gene implicated manganese (Mn) related brain phenotypes in the aetiology of schizophrenia." (PMID 35665764, 2022). "To uncover the role and potential biological implications of this missense variant in schizophrenia, we generated a knock-in mouse model (by introducing a Thr at p393 of mouse SLC39A8 (corresponds to the rs13107325 at p391 of human SLC39A8)) in this study." (PMID 36056013, 2022). "Several independent GWAS studies have revealed genetic associations between schizophrenia and functional missense variants in the SLC39A8 gene, which encodes the cation metal transporter ZIP86." (PMID 33608496, 2021). "In our study, we identified several Mn-related changes in human carriers of a missense variant in SLC39A8 associated with schizophrenia." (PMID 32753748, 2020). "A common missense variant in SLC39A8 is convincingly associated with schizophrenia and several additional phenotypes." (PMID 32753748, 2020). "The subsequent conjunctional FDR analyses pinpointed some specific loci that overlapped, including SLC39A8, a gene well-known for its high pleiotropy, being linked to a range of traits besides schizophrenia, including cognitive functioning." (PMID 30279459, 2020). "Our results show that a missense mutation in gene SLC39A8 is associated with larger gray matter volume in the putamen and that this association is significantly weakened in schizophrenia." (PMID 30649180, 2019). "In conclusion, this study provides new evidence of the association between SLC39A8 and schizophrenia." (PMID 31533672, 2019). "In conclusion, a new risk locus in Chinese Uygur population was identified in this study, providing new evidence of the association between SLC39A8 and schizophrenia." (PMID 31533672, 2019).
schizophrenia (continued). "The results of this study support that SLC39A8 is a susceptible gene for schizophrenia in the populations of Han Chinese and Uygur Chinese in China, further studies are suggested to validate the association." (PMID 31533672, 2019). "In this study, a case-control study was performed and a new risk genetic locus for schizophrenia, rs10014145, was found in SLC39A8 in the Chinese Uygur Ethnic population." (PMID 31533672, 2019). "On the basis of the collected results, we propose that the association of SLC39A8 with schizophrenia partly depends on its function in the transport of metal ions, particularly cadmium transportation and in the maintenance of brain homeostasis." (PMID 31533672, 2019). "The association between SLC39A8 and schizophrenia in European populations was discovered in multiple studies, and all researches then focused on the most pleiotropic variant, rs13107325." (PMID 31533672, 2019). "SLC39A8 is also implicated in schizophrenia, and genome-wide association studies (GWAS) now reveal shared genetic influences of the SLC39A8 gene on both schizophrenia and inflammatory bowel disease." (PMID 28713269, 2017). "A point mutation p.A391T in SLC39A8 has been associated with some disorders including schizophrenia." (PMID 26471164, 2016). "SLC39A8 mutations have also been associated with schizophrenia, mental retardation, and with cerebellar atrophy or cranial asymmetry with accompanying dysmorphologies." (PMID 27166256, 2016). "Moreover, the SLC39A8 A391T (rs13107325) variant has been reported to result in increased innate immune signaling, contributing to the pathogenesis of schizophrenia." (PMID 41232668, 2025). "Finally, CT- and SA-derived GIBNs were associated with schizophrenia risk variants in the SLC39A8 gene; namely rs13107325 was associated with CT5 and rs13135092 was associated with SA5." (PMID 39448598, 2024). "Interestingly, over the past decade, SLC39A8 polymorphisms have been largely shown to be associated with higher schizophrenia risk." (PMID 35745255, 2022). "SLC39A8 is also expressed in the brain, and SLC39A8 SNPs and mutations have been associated with specific brain structure alteration phenotypes by MRI; SLC39A8 polymorphisms have also been shown to be associated with higher schizophrenia risk." (PMID 35745255, 2022). "For example, SNP rs10014145 in SLC39A8 is associated with schizophrenia in Han and Uygur Chinese." (PMID 33790950, 2021). "Moreover, an “unbiased phenome-wide approach” was used in an attempt to understand phenotypic implications of the association of the SLC39A8 p.Ala391Thr variant with schizophrenia." (PMID 31521203, 2019). "In this imaging genetics study of brain structure, a significant association between a missense mutation in SLC39A8 (a gene previously associated with schizophrenia) and gray matter volume in putamen was discovered and replicated using 10 411 healthy participants from 5 independent studies." (PMID 30649180, 2019). "Variants of SLC39A8 are associated with a shift in gut microbiome composition, T cell immunity, lipid levels, blood pressure, and obesity, highlighting the relationship between schizophrenia, inflammation, and metabolic dysregulation." (PMID 28713269, 2017). "Additionally, SLC39A8 has been consistently identified as a risk variant for schizophrenia." (PMID 36180423, 2022). "Although we did not detect significant differences in many traits (associated with rs13107325 in humans) in SLC39A8-p.393T knock-in and wild-type mice, we validated the functionality of rs13107325 and our study indicate that rs13107325 may confer schizophrenia risk by affecting dendritic spines." (PMID 36056013, 2022). "As the SLC39A8 protein is highly conserved in mouse and human, we hypothesized this point-mutation mouse model can provide pivotal information for elucidating the potential pathogenesis of schizophrenia." (PMID 36056013, 2022).
schizophrenia (continued). "Thus, the SLC39A8 missense mutation is correlated with larger gray matter volume in the putamen, but this association is significantly weakened in patients diagnosed with schizophrenia." (PMID 31521203, 2019). "Although the significant association between SLC39A8 and schizophrenia in European Caucasian has been established, this study investigated whether the association between SLC39A8 and schizophrenia was also present in the Chinese Uygur population, which is considered to be genetically admixed." (PMID 31533672, 2019). "GWASs have linked rs13107325, a single nucleotide polymorphism (SNP) in SLC39A8, with diverse clinical phenotypes, including risk of inflammatory bowel disease (IBD), schizophrenia, and Parkinson’s disease, as well as cardiovascular and metabolic phenotypes." (PMID 41178719, 2025). "The index SNV rs13107325 at 4q24 locus (PLACO P = 1.78 × 10−14 for GERD-schizophrenia; PLACO P = 4.19 × 10−8 for GERD-PTSD) was a significant eQTL for SLC39A8 (OMIM 608732), which encodes ZIP8 metal cation transporter." (PMID 36753304, 2023). "Another highly pleiotropic locus, rs13135092 on SLC39A8, previously associated with high-density lipoprotein cholesterol (HDL) in current drinkers and schizophrenia, was a GWS locus associated with smoking cessation." (PMID 37147289, 2023). "In fact, some of these GWAS have shown that the missense mutation of the Solute Family 39 Gene (SLC39A8), which encodes the Zinc Transporter Protein (Zrt), and the Zrt- and Irt-like Protein 8 (ZIP8), is associated with schizophrenia." (PMID 35963926, 2022). "SLC39A8 is widely expressed in many tissues, including the brain and is one of the most significantly up-regulated genes in schizophrenia." (PMID 31533672, 2019). "Given that the major function of the SLC39A8 gene is accessible to pharmacologic manipulation, we believe that these results are crucial for discovering novel treatment for schizophrenia." (PMID 30649180, 2019). "Several variants in SLC39A8 have been associated with rare monogenic diseases, such as CDG type IIn and Leigh syndrome, as well as more common polygenic diseases including IBD, cardiometabolic disease, schizophrenia, and Parkinson’s disease, among others." (PMID 41178719, 2025). "Of note, our finding is consistent with results observed in schizophrenia cases (i.e., decreased dendritic spine density), indicating that SLC39A8-p.393T could regulate dendritic spine morphogenesis." (PMID 36056013, 2022). "Finally, we investigated the impact of SLC39A8-p393T on dendritic spine density and synaptic transmission, a potential pathology of schizophrenia." (PMID 36056013, 2022). "In addition, gene expression pattern and epigenetic regulation provide additional evidence that SLC39A8 is relevant to schizophrenia." (PMID 31533672, 2019). "Therefore, targeting SLC39A8 to treat schizophrenia or coronary is highly problematic, whereas treatment of AEZ (e.g., Zn supplementation) can be relatively straightforward." (PMID 31521203, 2019). "The aberrant expression pattern of SLC39A8 may indicate that the gene is involved in the genesis of schizophrenia." (PMID 31533672, 2019). "While nearly all common genomic variants associated with schizophrenia have no known function, one corresponds to a missense variant associated with change in efficiency of a metal ion transporter, ZIP8, coded by SLC39A8." (PMID 30696806, 2019). "SNPs in SLC39A8 and SLC30A10 have previously been associated with neurological outcomes; SLC39A8 SNPs have been linked to schizophrenia, chronic stress, and mental disability, and SLC30A10 genotypes were associated with neurological performance in elderly people." (PMID 30619481, 2018). "Furthermore, in the comparison of the post-mortem human brain tissue of schizophrenia patients and healthy controls, SLC39A8 is one of the most differentially methylated genes in CpG islands of the promoter region, as determined by genome-wide DNA methylation analysis." (PMID 31533672, 2019).
schizophrenia (continued). "In particular, while the proximal function of the SLC39A8 gene product, ZIP8, is known, the implications of the schizophrenia risk gene are not." (PMID 30696806, 2019).
Crohn disease (13 papers, 2019 to 2025). A gastrointestinal disorder characterized by chronic inflammation involving all layers of the intestinal wall, noncaseating granulomas affecting the intestinal wall and regional lymph nodes, and transmural fibrosis. "Genetic variants of SLC39A8 have been associated with a variety of human diseases, including neuropsychiatric disorders, Crohn's disease, and obesity." (PMID 41232668, 2025). "A SLC39A8 (ZIP8 A391T) variant identified in genome-wide studies disrupts the regulation of multiple metals, including Mn, and increases susceptibility to Crohn’s disease." (PMID 41476579, 2025). "The Crohn’s disease-associated variant rs13107325 in the SLC39A8 gene results in an A391T substitution in the ZIP8 metal ion transporter and has previously been linked to alterations in the colonic microbiome in variant carriers." (PMID 39322808, 2024). "We and others have recently reported that the coding single-nucleotide polymorphism (SNP) rs13107325 in the gene SLC39A8 resulting in the Ala391Thr substitution in the ZIP8 metal ion transporter is associated with Crohn’s disease." (PMID 39322808, 2024). "We report here, for the first time, that the Crohn’s disease linked missense variant in SLC39A8 modulates colonic microbiome composition, consistent with what has previously been reported in human Crohn’s disease patients and in healthy control variant carriers." (PMID 39322808, 2024). "An alanine-to-threonine change at position 391 of ZIP8 resulting from a nonsynonymous SNP (rs13107325C→T) in SLC39A8 is associated with a variety of diseases including Crohn's disease, severe idiopathic scoliosis, and circulating lipid levels and risk of coronary artery disease." (PMID 33485965, 2021). "While gene variants of the human SLC39A8 gene have been associated with Crohn’s Disease its function in intestinal epithelial cells is not clear and requires additional study." (PMID 35779631, 2022).